HOTAIRM1 (HOXA transcript antisense RNA, myeloid-specific 1)
Diseases named in the same sentence as HOTAIRM1 in open-access papers (continued):
Sharing a sentence is not in itself a finding about the gene and the disease.
glioma (continued). "HOTAIRM1 is revealed to facilitate the malignant progression of glioma." (PMID 38012763, 2023). "Furthermore, rescue assays were conducted to explore the regulatory function of HOTAIRM1/METTL3/IGFBP2 in glioma cell cellular processes and VM formation." (PMID 38012763, 2023). "Moreover, CD34-PAS immunohistochemical staining showed that glioma cell VM density was significantly increased under HOTAIRM1 overexpression and prominently reduced under HOTAIRM1 depletion." (PMID 38012763, 2023). "In addition, a correlation between high HOTAIRM1 levels and poor clinical outcomes was observed in glioma patients." (PMID 36321132, 2022). "HOTAIRM1 is a lncRNA that has been verified as an oncogene in glioma progression; however, whether it is involved in the maintenance of the malignant phenotype of tMSCs has never been studied." (PMID 35586206, 2022). "In conclusion, we report that HOTAIRM1 is conducive to maintaining the malignant phenotype of tMSCs transformed by GSCs in the glioma microenvironment via E2F7 by binding to FUS and that the HOTAIRM1/FUS/E2F7 axis may be a potential target for glioma therapy." (PMID 35586206, 2022). "They observed elevated levels of HOTAIRM1 in both glioma cells and t-FBs." (PMID 36321132, 2022). "To determine effects of genetic knock-down of HOTAIRM1 in glioma cells, we first performed a transient siRNA-mediated knock-down of HOTAIRM1 in the four established glioblastoma cell lines U251MG, LN-229, LN-18, and T98G, which showed an intermediate expression level." (PMID 34584066, 2021). "Moreover, HOTAIRM1 has been proposed to promote glioma growth by acting as a sponge for several tumor suppressive miRNAs." (PMID 34584066, 2021). "HOTAIRM1 knock-down significantly reduced cell viability of these glioma lines by 20–30%." (PMID 34584066, 2021). "Our results verified malignant transformation of fibroblasts in glioma microenvironment induced by GSCs, and further disclosed that HOTAIRM1 played active roles on malignancy phenotype of t-FBs, which could be a potential target against gliomas." (PMID 33816233, 2021). "Since radiation sensitivity has been associated with intracellular ROS levels, the modulation of ROS levels by HOTAIRM1 shown in our study suggests HOTAIRM1-mediated reduction of intracellular ROS as a potential mechanism contributing to glioma radioresistance." (PMID 34584066, 2021). "Collectively, these data suggest that HOTAIRM1 may promote glioma growth and therapy resistance by sponging hsa-miR-17-5p, and thereby increasing TGM2 transcript and protein levels." (PMID 34584066, 2021). "Studies have shown that some lncRNAs such as HOTAIRM1 and colon cancer-associated transcript 2 (CCAT2), associated with tumorigenesis and cancer development, were upregulated in glioma, while other lncRNAs showing tumor-suppressive functions, such as RP11-838N2.4 and MALAT1, were downregulated." (PMID 34202078, 2021). "In addition, the lncRNA HOTAIR myeloid-specific 1 (HOTAIRM1), whose expression is upregulated in glioma, enhances malignancy via sponging of miR-129-5p as ceRNA and is also related to immune activation that promotes T cell-mediated immune responses." (PMID 33980320, 2021). "HOTAIRM1 knock-down caused reduced colony formation capacity of glioma cells already in non-irradiated cells." (PMID 34584066, 2021). "In addition, HOTAIRM1 knock-down resulted in significant reduction of glioma cell invasiveness by 40–50% and colony formation capacity by 25–40%." (PMID 34584066, 2021). "lncRNA HOTAIRM1 could be used as the prognostic biomarker for glioma patients and a potential target for the treatment of gliomas." (PMID 33330055, 2020). "Similarly, we quantified HOTAIRM1 levels in five normal brain tissue samples and 15 glioma samples that included three World Health Organization (WHO) glioma grades." (PMID 33323548, 2020). "Thus, additional experiments are needed to clarify the biological function and molecular mechanisms of HOTAIRM1 in glioma." (PMID 31477638, 2019).
glioma (continued). "We also examined the function of HOTAIRM1 by gene silencing in glioma cell lines." (PMID 31477638, 2019). "We performed PCA to investigate the functional significance of HOTAIRM1 overexpression in glioma." (PMID 31477638, 2019). "Additionally, we used rescue assays to explore whether METTL3 was involved in HOTAIRM1-mediated glioma cell malignancy and VM formation." (PMID 38012763, 2023). "However, whether HOTAIRM1 is involved in glioma VM formation and its mechanism of regulating VM remain unclear." (PMID 38012763, 2023). "Therefore, we hypothesized that HOTAIRM1 might promote glioma cell malignancy and facilitate VM formation through this mechanism." (PMID 38012763, 2023). "Thus, we attempted to clarify the role and mechanism of HOTAIRM1 in VM formation in glioma." (PMID 38012763, 2023). "Besides, HOTAIRM1 can promote glioma progression through certain ceRNA networks." (PMID 33816233, 2021). "Therefore, the HOTAIRM1/miR-133b-3p/TGFβ signal axis may serve as the potential therapeutic target against t-FBs in glioma microenvironment." (PMID 33816233, 2021). "However, we observed an additional, dose-dependent decrease in colony formation of HOTAIRM1 knock-down glioma cells after irradiation compared to irradiated control-transfected glioma cells which was not caused by an alteration in HOTAIRM1 expression levels." (PMID 34584066, 2021). "Thus, HOTAIRM1 expression is correlated with clinical and molecular features of glioma." (PMID 31477638, 2019). "In addition, HOTAIRM1 expression was associated with the grade malignancy of brain tumor, and HOTAIRM1 levels of high-grade glioma (WHO III and IV) were significantly higher than low-grade glioma (WHO I and II)." (PMID 30376874, 2018). "By downregulating HOTAIRM1, a significant inhibition of EMT in glioma is evidenced by the decrease in mesenchymal cell markers and the simultaneous increase in epithelial cell markers." (PMID 39553554, 2024). "Conversely, increased expression of HOTAIRM1 was relevant to the limited clinical efficacy of temozolomide (TMZ) treatment, while knocking down HOTAIRM1 resulted in a lower IC50 in two glioma cell lines for TMZ." (PMID 39553554, 2024). "This suggests that HOTAIRM1 not only boosts malignancy and influences the TME in glioma by sequestering hsa-miR-495-3p and hsa-miR-129-5p but also by strengthening certain hub gene expression in a non-ceRNA manner." (PMID 39553554, 2024). "HOTAIRM1, post-transcriptionally stabilized by METTL3, promotes VM formation in glioma via up-regulating IGFBP2 expression, which provides a new direction for glioma therapy." (PMID 38012763, 2023). "HOX antisense intergenic RNA myeloid 1(HOTAIRM1) is a member of the HOX family, which is critically involved in glioma progression." (PMID 38012763, 2023). "However, the regulatory mechanism of HOTAIRM1 in glioma VM remains unclear." (PMID 38012763, 2023). "Our data showed that HOTAIRM1, post-transcriptionally stabilized by METTL3, bound to IGFBP2, suggesting that HOTAIRM1 promotes VM formation in glioma via up-regulating IGFBP2 expression, providing a theoretical basis for new glioma treatment methods." (PMID 38012763, 2023). "Collectively, HOTAIRM1/miR-133b-3p/TGFβ axis was involved in modulating t-FBs malignancy in TME remodeled by GSCs, which had the potential to serve as a target against gliomas." (PMID 33816233, 2021). "In this study, we investigated the lncRNA HOTAIRM1, which is overexpressed in GBM tissues compared with low-grade glioma and normal brain tissues." (PMID 33323548, 2020). "They linked some previously glioma-associated lncRNAs, like H19, CRNDE, and HOTAIRM1, with recurrence, and also defined new lncRNAs, like AC016745.3, XLOC_001711, and RP11-128A17.1, which their lncRNA–mRNA co-expression analysis indicated might have critical roles in glioma recurrence." (PMID 32650527, 2020). "However, the prognostic value of HOTAIRM1 in glioma remains unknown." (PMID 31477638, 2019).
glioma (continued). "To evaluate the impact of HOTAIRM1 on the tumor microenvironment (TME), we calculated immune and stromal scores and tumor purity in glioma specimens of TCGA and CGGA datasets." (PMID 31477638, 2019). "HOTAIRM1 was shown to promote tumor malignancy by directly regulating HOXA1 expression in lung cancer and glioma." (PMID 31477638, 2019). "Small interfering (si)RNA-mediated knockdown of HOTAIRM1 expression in the U87 and LN229 glioma cell lines decreased HOTAIRM1 transcript level 48 h later." (PMID 31477638, 2019). "HOTAIRM1 was abnormally up-regulated in GBM tissues and cells, and this up-regulation was correlated with grade malignancy in glioma patients." (PMID 30376874, 2018). "Two lncRNAs, colorectal neoplasia differentially expressed (CRNDE) and HOX antisense intergenic RNA myeloid 1 (HOTAIRM1), showed the highest expression in glioma (grade I‐IV) compared with that in normal tissue." (PMID 30117678, 2018). "HOTAIRM1 can positively regulate IGFBP2 expression, and IGFBP2 binds with HOTAIRM1 via METTL3-mediated m6A binding-domains and increases its stability and expression in glioma tissues and cells." (PMID 39691597, 2024). "Thus, by competing with miR-133b-3p, HOTAIRM1 increased TGFB1 expression and TGF-β signaling in gliomas." (PMID 38571882, 2024). "Notably, the function of IGFBP2 in glioma cell malignancy and VM was found to be partially countervailed when overexpressing HOTAIRM1 in IGFBP2 silenced U251 cells or silencing HOTAIRM1 in IGFBP2 overexpressing U251 cells." (PMID 38012763, 2023). "Thus, we detected the expression of E2Fs in HOTAIRM1-overexpressed tMSCs and found that E2F7, which has been reported to act as an oncogene in glioma, was also obviously increased." (PMID 35586206, 2022). "Collectively, this study revealed that the HOTAIRM1/FUS/E2F7 axis is involved in the maintenance of the malignant phenotype of tMSCs and may function as a novel target for glioma therapy." (PMID 35586206, 2022). "For example, the expression of homeobox A transcript antisense RNA myeloid-specific 1 (HOTAIRM1) is positively correlated with WHO grade as well as histopathologic classification according to both The Cancer Genome Atlas (TCGA) and Chinese Glioma Genome Atlas (CGGA) sets." (PMID 34202078, 2021). "Furthermore, HOTAIRM1 levels gradually increased with increasing WHO grade, and grade IV gliomas (GBMs) had the highest level of HOTAIRM1." (PMID 33323548, 2020). "Given that EMT is closely related to an immunosuppressive status, we speculate that HOTAIRM1 promotes EMT to reprogram immune and inflammatory responses within the glioma microenvironment." (PMID 31477638, 2019). "LncRNAs that are involved in both embryogenesis and glioma biology (e.g: CRNDE, HOTAIRM1, ADAMTS9‐AS2), with expression levels controlled by epigenetic mechanisms, could represent a future option for further studies on epigenetic therapy for glioma patients." (PMID 30117678, 2018). "In addition, the expression profiles analysis in recurrent gliomas compared with primary gliomas identified abundant differentially expressed lncRNAs, such as H19, CRNDE, and HOTAIRM1." (PMID 28293170, 2017). "Furthermore, we also found that the luciferase activities showed no significant change with mutant binding site of IGFBP2 in glioma cells after HOTAIRM1 down-regulation." (PMID 38012763, 2023). "Our study revealed that the HOTAIRM1/FUS/E2F7 axis is involved in the malignant progression of tMSCs transformed by GSCs in the glioma microenvironment and may function as a novel target for glioma therapy." (PMID 35586206, 2022). "Given the HOX gene widespread reactivation and their functional role in glioma and GSC, it can be hypothesized that HOXA-AS2 collaborates with some of them in this process, such as the lncRNA HOTAIRM1 that is overexpressed in both IDHwt samples and GSCs, such as HOXA-AS2." (PMID 35563134, 2022).
glioma (continued). "In glioma, studies have shown that HOTAIRM1 can maintain the tumourigenesis of GSCs and promote the proliferation, migration, and invasion of glioma cells; however, its role in tMSCs in the glioma environment has never been studied." (PMID 35586206, 2022). "Moreover, they showed increased expression of HOX antisense intergenic RNA myeloid 1 (HOTAIRM1) and decreased expression of RFPL1 antisense RNA 1 (RFPL1S) as the malignancy progressed; i.e., in glioblastoma compared to low-grade glioma and the reference samples." (PMID 32650527, 2020). "Subsequently, RIP assay illustrated that both IGFBP2 and HOTAIRM1 were markedly enriched in immunoprecipitation through bio-HOTAIRM1 beads rather than control, supporting the binding relation of IGFBP2 with HOTAIRM1 in glioma cells." (PMID 38012763, 2023). "At present, the relationship between HOTAIRM1 and IGFBP2 in glioma cell and VM formation has not been investigated." (PMID 38012763, 2023). "We observed a similar expression pattern for HOTAIRM1 but not for HOTAIR, two HOX lncRNAs involved in glioma biology." (PMID 35563134, 2022).
glioblastoma (22 papers, 2018 to 2024). The most malignant astrocytic tumor (WHO grade IV). "We identified HOTAIRM1 as a candidate lncRNA whose up-regulation is significantly associated with shorter survival of glioblastoma patients, independent from IDH mutation and MGMT promoter methylation." (PMID 34584066, 2021). "The clinical significance of HOXA Transcript Antisense RNA, Myeloid-Specific 1 (HOTAIRM1) was determined by analyzing HOTAIRM1 in multiple glioblastoma gene expression data sets for associations with prognosis, as well as, IDH mutation and MGMT promoter methylation status." (PMID 34584066, 2021). "We have collected compelling evidence from several independent data sets that high HOTAIRM1 expression is linked to clinical aggressiveness and shorter survival of glioblastoma patients and that gene copy number gain is a likely cause of increased HOTAIRM1 expression levels in glioblastoma." (PMID 34584066, 2021). "Another study demonstrated that HOTAIRM1 promotes cell proliferation and invasion in human glioblastoma by upregulating SP1 via sponging miR-137." (PMID 39015773, 2024). "For instance, lncRNA HOTAIRM1 facilitates glioblastoma multiforme (GBM) progression by mediating H3K9 and H3K27 histone demethylation and reduces DNA methylation levels by sequestering DNA methyltransferases away from the TSS of the HOXA1 gene." (PMID 37993428, 2023). "It was a tumor suppressor in glioblastoma multiform, and downregulation of HOTAIRM1 usually inhibited tumor growth and invasion by regulating HOXA1 expression." (PMID 35350655, 2022). "For instance, lncRNA MIR22HG regulates GBM progression through Wnt/β-catenin signaling, whereas HOTAIRM1 promotes tumor aggressiveness and radiotherapy resistance in glioblastoma." (PMID 35191808, 2022). "LncRNA HOTAIRM1 (a type of long non-coding RNA) plays a role in glioblastoma proliferation and invasion, and its downregulation can regulate glioblastoma radiosensitivity in vitro and in vivo." (PMID 35628460, 2022). "The upregulation of HOX antisense intergenic RNA myeloid 1 (HOTAIRM1) has been shown to be associated with radiotherapy resistance and shorter patient survival in glioblastoma patients." (PMID 36499136, 2022). "HOTAIRM1 knock-out reduces cell viability, invasion, proliferation, and colony formation of glioblastoma cells through decreased expression of TGM2 (transglutaminase 2) and improves radiation sensitivity." (PMID 36499136, 2022). "In leukemia 38, glioblastoma 39, 40, non-small cell lung cancer 41, 42 and thyroid cancer 43, the expression of HOTAIRM1 is upregulated and it functions as an oncogene." (PMID 35711826, 2022). "HOTAIRM1 knock-down decreased expression of transglutaminase 2 (TGM2), a candidate protein implicated in mitochondrial function, and knock-down of TGM2 mimicked the phenotype of HOTAIRM1 down-regulation in glioblastoma cells." (PMID 34584066, 2021). "Our data support a role for HOTAIRM1 as a driver of biological aggressiveness, radioresistance and poor outcome in glioblastoma." (PMID 34584066, 2021). "After targeting HOTAIRM1 expression in glioblastoma cell lines, the oncogenic potential of these cells was diminished and RNA sequencing and mass spectrometry data suggested impaired mitochondrial function." (PMID 34584066, 2021). "Glioblastoma cell line models uniformly showed reduced cell viability, decreased invasive growth and diminished colony formation capacity upon HOTAIRM1 down-regulation." (PMID 34584066, 2021). "Here, we extend these findings by providing further clinical and functional evidence implicating HOTAIRM1 as a driver of tumor aggressiveness that contributes to radioresistance and poor outcome of glioblastoma patients." (PMID 34584066, 2021). "HOTAIRM1 can promote glioblastoma progression, but in ccRCC, it is downregulated, serving as a suppressor of HIF1-dependent angiogenic pathways." (PMID 34040677, 2021).